F8A2 (coagulation factor VIII associated 2)
Description:
RAB5A effector molecule that is involved in vesicular trafficking of early endosomes. Mediates the recruitment of HTT by RAB5A onto early endosomes. The HTT-F8A1/F8A2/F8A3-RAB5A complex stimulates early endosomal interaction with actin filaments and inhibits interaction with microtubules, leading to the reduction of endosome motility.
Synonyms: HAP40
Gene: Protein-coding gene on chromosome X (155,382,095 to 155,383,801, forward strand). Ensembl gene ENSG00000288709.
Subcellular location: Cytoplasm; Nucleus; Early endosome; Nucleus, nuclear body
Gene Ontology:
Molecular function: protein binding
Biological process: negative regulation of proteasomal protein catabolic process; endosomal transport; vesicle cytoskeletal trafficking
Cellular component: cytoplasm; early endosome; nucleus; nuclear body
Homologues: Orthologues: chimpanzee F8A1 (99% identical), rat F8a1 (86% identical), mouse F8a (85% identical), tropical clawed frog f8a1 (53% identical), zebrafish f8a (51% identical), Drosophila melanogaster Hap40 (22% identical). Paralogues in human: F8A1 (100% identical), F8A3 (100% identical).
Diseases named in the same sentence as F8A2 in open-access papers:
F8A2 is named in the same sentence as 3 diseases in open-access papers, as found by Europe PMC text mining. Sharing a sentence is not in itself a finding about the gene and the disease. The quoted sentences say what the papers report.
cancer (1 paper, 2021). A tumor composed of atypical neoplastic, often pleomorphic cells that invade other tissues. "However, despite their proximity and encoding the identical protein, F8A1, F8A2 and F8A3 each have highly distinct patterns of expression across the thousands of samples of tissues and cancers in the TCGA/GTEx dataset, indicating they may participate in different or overlapping biological scenarios." (PMID 33972602, 2021).
F8A2 also shares sentences with these, for which no sentence is quoted: autism (1 paper); COVID-19 (1).